NF1 (neurofibromin 1)
Diseases named in the same sentence as NF1 in open-access papers (continued):
Sharing a sentence is not in itself a finding about the gene and the disease.
tumor (continued). "It functions as a molecular sponge for miR-107, thereby regulating NF1 expression and promoting tumor development." (PMID 41463204, 2025). "Other tumour driver genes (NF1, ATRX, PIK3R1, SPTA, and PIK3CA) marked by IntOGen,54 were also found among the top 12 mutated genes." (PMID 41292185, 2025). "In patients with NF1, loss of NF1 results in excessive RAS activation that drives the RAF-MEK-ERK cascade, leading to cell hyperproliferation and tumor formation." (PMID 41022755, 2025). "Special attention should be given to tumor size, as it is the only macroscopic criterion for neoplastic progression in NF-1 patients with small intestinal involvement." (PMID 40563584, 2025). "The kinetics of pERK modulation was also investigated with tovorafenib in the NF1-LOF tumor cell lines." (PMID 40111124, 2025). "The significantly higher frequency of NF1, ACVR1, MAP2K1, and AKT1 mutations in EOCRC H/L patient data support the call for expanded investigation into their biological significance in tumor development and treatment response." (PMID 40227607, 2025). "In segmental mosaicism, the features of NF1 are restricted to one or more segments of the body and are responsible for regional skin pigmentation, tumour growth, and limb hypertrophy." (PMID 39254838, 2025). "A self‐assembled peptide (NF‐1) targeting tumor cell Golgi apparatus (GA) is tailored for effective immunotherapy via reshaping the MIF‐mediated immunosuppressive network." (PMID 39908165, 2025). "For these reasons, we conducted a multi-center retrospective cohort study to evaluate the impact of tumor location on long-term outcomes for children with NF1-LGG." (PMID 40296988, 2025). "A targeted Exos-based quadruple combination therapy significantly reduced tumor burden in vivo, suggesting a promising strategy for addressing tumor progression and TMZ resistance in NF1-mutated GBM." (PMID 40565099, 2025). "Despite their clinical significance, the molecular mechanisms driving these tumor types in the context of NF1 remain poorly understood." (PMID 41294711, 2025). "While several studies emphasise the role of methylation in modifying NF1 tumour behaviour and phenotype, other findings indicate that promoter methylation of the NF1 gene itself is not a primary driver of gene silencing." (PMID 40843672, 2025). "We discuss potential molecular mechanisms underlying this transformation, with mutations in NF1, PBRM1, and FAT1 likely contributing to the tumor's atypical morphology and loss of melanocytic markers." (PMID 40125165, 2025). "These tumor manifestations result from activated RAS due to reduced functional levels of the NF1 gene product, the GTPase-activating protein (GAP) neurofibromin." (PMID 41022755, 2025). "In a GBM model derived from neural stem cells with engineered Nf1/Pten co-deletion and EGFRvIII overexpression, aggressive tumor growth and infiltration were observed compared to an Nf1/Pten-only tumor." (PMID 40331985, 2025). "First, in vitro experiments demonstrate that NF‐1 can selectively and effectively disrupt tumor cell GA and induce tumor cell apoptosis." (PMID 39908165, 2025). "In vitro anti-proliferative activity of tovorafenib and pathway modulation was evaluated in NF1-LOF tumor cell lines." (PMID 40111124, 2025).
tumor (continued). "Neurofibromas (Nf) originate from precursor cells of Schwann cells and are proliferations of both tumour cells (NF1−/−) sharing characteristics with unmyelinated Schwann cells and non-tumour Schwann cells (NF1+/−)." (PMID 41247561, 2025). "Trametinib was proposed for each case after discussion in the molecular tumor board based on preclinical rationale, suggesting that MEK inhibition can be effective in NF1-deficient tumors, and by extrapolation from evidence in other NF1-altered cancers." (PMID 41170454, 2025). "Clinically, cohorts differed in patient demographics (e.g., NF1-related vs. sporadic cases), tumor size, grade, location, and treatment strategies (margin status, radiotherapy, and chemotherapy)." (PMID 40563647, 2025). "Conversely, while KIT mutant cases showed an equal distribution in primary tumor site, NF1-mutant cases had an exclusive small intestine localization (9/9), and PDGFRA-mutant cases had gastric localization only (18/18)." (PMID 41407759, 2025). "Key genetic alterations include mutations in BRAF, NF1, and PTEN, elevated mTOR expression, and specific miRNA profiles, which influence tumour progression and response to therapy." (PMID 40831998, 2025). "Other mutations of note include JAK3 (10% patient tumours, 25% cell lines, 33% PDX models) and NF1 (10% patient tumours, 0% cell lines, 25% PDX models)." (PMID 40415599, 2025). "Expression of the tumor suppressor markers NF1 and PTEN was significantly decreased in nucleofected organoids when compared to control organoids and GFP+ cells." (PMID 40917877, 2025). "The ST88-14 human MPNST cell line was chosen for its deficiency of NF1, its sensitivity to GRDC24 and its reliable tumor formation in the sciatic nerve, making it a suitable orthotopic model for vector selection and validation." (PMID 41022755, 2025). "The H/L patients exhibited higher frequencies of NF1, CBL, MAPK3, and BMPR1A mutations, underscoring the need for further research into their functional roles in tumor progression." (PMID 40282501, 2025). "The NF1 gene is a tumor suppressor that contributes to cancer development and has been associated with gastrointestinal tract adenocarcinoma." (PMID 40458721, 2025). "NF1 expression was analyzed via quantitative polymerase chain reaction (qPCR) in blood and tumor cDNA." (PMID 39968302, 2025). "The study population included 99 children 18 years of age or younger at the time of initial diagnosis of NF1-LGG who received treatment for their target tumor between 1999 and 2021." (PMID 40296988, 2025). "Adults with NF1 who live in the United States and speak English were recruited through the Children's Tumor Foundation's (CTF) NF Registry, CTF's NF Clinic Network, and the Neurofibromatosis Network." (PMID 40361300, 2025). "By leveraging insights into the Ras–MAPK pathway, these therapies aim to reduce tumor burden and enhance the quality of life for individuals with NF1." (PMID 40725763, 2025). "The recently published ERN GENTURIS tumor surveillance guidelines for individuals with NF1 provide compelling evidence for the proposed screening efforts." (PMID 39264447, 2025). "The ipNF95.11bC (NF1-/−) and ipnNF95.11c (NF1+/−) were immortalized from the same pNF patient using the tumor tissue and tumor-adjacent non-tumor Schwann cells, respectively." (PMID 40723243, 2025). "As with NF1 mutations, KRAS mutations increase tumor-promoting immune cell function in the TME, which suggests these compounds offer a promising new therapeutic strategy for PNF and MPNST." (PMID 40563570, 2025).
tumor (continued). "In NF1-LOF tumor cells treated with tovorafenib, an increase in phosphorylated ERK was observed at low concentrations, with inhibition of phosphorylated ERK at higher concentrations." (PMID 40111124, 2025). "In this field, tumor segmentation and classification methods in WSI using DL have developed significantly in recent years; however, they have been applied to NF1-associated tumors only rarely." (PMID 41168866, 2025). "This is despite the fact that the tumor tissue in the Nf1 +/+ mice had a longer time to grow, on average." (PMID 39804140, 2025). "One patient with a PV in the NF1 gene underwent an exam that was able to identify metastases following tumor recurrence, which made treatment with 131I-mIBG possible." (PMID 40758282, 2025). "The NF1 gene is a tumor suppressor gene localized to chromosome 17q11.2,1,6 which encodes the protein neurofibromin." (PMID 40697342, 2025). "The neurofibromin-1 (NF-1) gene is located on the long arm of chromosome 17 (17q11.2) and functions as a tumour suppressor gene." (PMID 39254838, 2025). "Previous studies have identified C/EBPα, C/EBPβ and NF-1 as tumor suppressors, whereas AP-2α acts as an oncogene." (PMID 41020879, 2025). "The levels of pERK were measured using MSD ELISA 1 hour after treatment in three NF1-LOF tumor cell lines, including sNF96.2, MeWo, and NCI-H1838." (PMID 40111124, 2025). "Cox regression was performed for tumor size and tumor grade, with further adjustments for age and sex, as well as separately for NF1 status and the presence of metastases at diagnosis." (PMID 41272396, 2025). "Little anti-proliferative activity was observed in the NF1-LOF tumor cell lines treated with tovorafenib." (PMID 40111124, 2025). "A series of drug combination studies has demonstrated effectiveness in NF1-associated MPNSTs, including a combination of a SHP2 inhibitor and MEKi, which targets multiple vulnerabilities within the tumor." (PMID 40723243, 2025). "The whole-exome sequencing revealed a variety of common oncogenic mutations in the original tumor and HMucBOT-2, including KRAS, ARID1A, ARID1B, and NF1, while CDKN2A remained wild-type." (PMID 40427213, 2025). "By optimizing the GAP-related domain (GRD), we discovered that altering its length significantly impacts expression levels and, consequently, the anti-tumor effectiveness when delivered via an AAV vector in NF1 null cell lines." (PMID 41022755, 2025). "Differences in reported survival outcomes can be attributed to patient-specific factors, such as sex, age, and NF1 status, and tumor-related factors, such as size, location, grade, genetics, systemic treatment, and extent of surgical resection." (PMID 40563647, 2025). "They showed that most children with NF1-related PN experienced lasting tumor reduction and continued pain improvement beyond what was previously reported at 1 year, with no new safety signals identified." (PMID 41440192, 2025). "Since TSO500 does not report CNVs for NF1, a retrospective bin count analysis of NF1 in the tumor DNA was conducted and confirmed a somatic NF1 deletion." (PMID 39794422, 2025). "To understand the differences in pERK modulation in response to tovorafenib in the BRAF fusion versus NF1-LOF setting, we further evaluated pERK modulation in three NF1-LOF tumor cell lines in vitro." (PMID 40111124, 2025). "NF1 was normal in all cases, except for HCB-GIC1, where the original tumor sample presented cnLOH loss, in mosaicism, whereas the GIC-derived showed only loss." (PMID 41009470, 2025). "The anti-proliferative activity of tovorafenib and TAK-632 was evaluated by CTG cell viability assay at 72 hours after treatment in the NF1-LOF tumor cell lines and the BRAF V600E tumor cell line, A375." (PMID 40111124, 2025).
tumor (continued). "Treating OPG is influenced by factors such as tumor size, growth rate, patient age, tumor location in the optic pathway, visual status, and the presence of an NF–1 diagnosis." (PMID 40867225, 2025). "A Phase 2a clinical trial in NF1 patients with cNFs demonstrated that NFX-179 significantly reduced tumor development." (PMID 41294711, 2025). "GISTs represent a histological tumor category that occurs with increased frequency in patients with NF-1 and, more specifically, is observed in the small intestine." (PMID 40563584, 2025). "Using this strategy, lamotrigine emerged as the most promising therapy for limiting tumor progression and vision loss in Nf1-OPG mice, relevant to clinical translation for children with NF1-OPG." (PMID 41497446, 2025). "The neurofibromin 1 (NF1) gene encodes for a small GTPase-activating protein that binds to the RAS family of proteins and functions as a tumor-suppressor gene." (PMID 41170454, 2025). "While the role of T cells in NF1 is poorly understood, their distribution across different tumor stages suggests a dynamic involvement in disease progression." (PMID 40563570, 2025). "Tumor-suppressor genes, including APC, BARD1, HMMR (RHAMM), KLLN, LZTR1, MCPH1 (BRIT1), MLH1, NF1, RB1CC1 (FIP200), SLC22A18, and SPTBN1, have been found to increase the risk of disease and tumor development." (PMID 40941673, 2025). "The kinetics of the pERK increase at lower concentrations differed across the NF1-LOF tumor cell lines." (PMID 40111124, 2025). "While Nf1-KO mice develop rare small cNFs from 1 year of age, we demonstrated that skin trauma promotes tumor formation." (PMID 40684195, 2025). "Further features, such as NF1 loss, MAP2K1 mutations, ERBB2 activation, and frequent copy number changes (including CDKN2A/2B deletion and 1p/1q imbalances), add to tumor heterogeneity and evolution." (PMID 41376748, 2025). "As NF1 is a tumor suppressor gene, it is a GTPase-activating protein (GAP) which negatively regulate Ras signaling." (PMID 40761243, 2025). "Epigenetic alterations, particularly DNA methylation, histone modifications, and the dysregulation of ncRNAs, have been shown to influence key cellular pathways relevant to tumour development, progression, and clinical heterogeneity in NF1 and NF2." (PMID 40843672, 2025). "Together, these profiling layers help position ANNUBP along the NF1 tumor continuum and provide a practical framework for monitoring progression." (PMID 41463204, 2025). "The NF1-LOF MPNST tumor cell line, sNF96.2, was sensitive to tovorafenib with a proliferation EC50 of 0.99 μmol/L, which was comparable with the A375 EC50 proliferation." (PMID 40111124, 2025). "Cluster 2 encompasses amongst others pathogenic variations in the RET-, NF1-, or MAX-genes, resulting in tumour development via overactivation of the tyrosine kinase." (PMID 41276740, 2025). "Although some NF1 PN tumor cells have been shown to form xenograft tumors, they are very slow growing and require signaling from NF1−/− peripheral nerves within the tumor microenvironment." (PMID 39129390, 2025). "A series of elegant experiments have revealed that optic nerve gliomas were not developed or developed as small and less proliferative in NF1-OPG mice that were reared in the dark during time periods typical for tumor initiation and growth." (PMID 40806554, 2025). "New important data demonstrated that NF2 inactivation drove the activation of p21-activated kinases (PAKs) signaling, which initiated NF1-mutant SC tumor dedifferentiation and resistance to therapy." (PMID 40940747, 2025).
tumor (continued). "In patients with a genomic tumor profile (n = 204), the NF1 gene alteration was identified as an independent predictor of distant progression (HR: 3.48, 95% CI: 1.48–8.21, P = .004) and poor survival." (PMID 40575417, 2025). "In summary, we have tailored a tumor cell GA‐targeting self‐assembled peptide (NF‐1) for effective immunotherapy via reshaping the MIF‐mediated immunosuppressive network." (PMID 39908165, 2025). "We found a significant increase in the 24 kDa fragment of cleaved PARP relative to total PARP in xenografts from both CQ and selumetinib‐treated mice, indicating that both drugs resulted in cell apoptosis in the NF1 xenografts, thus slowing tumor growth." (PMID 39129390, 2025). "They further showed that LAG3 and PD-L1 targeting therapies inhibit metastasis in NF1-, TSC1-, or TGF-β RII-deficient tumours." (PMID 40650785, 2025). "Mutations in neurofibromatosis-related protein (NF1), NRAS, and HRAS genes were found in tumours that developed resistance to lorlatinib or ceritinib, and NF1 loss conferred resistance to ALK inhibitors in NB cells." (PMID 41511287, 2025). "Together, this suggests that SCs play an important role in the onset of hypersensitivity in NF1 before tumor formation but during Remak bundle disruption." (PMID 38258905, 2024). "Since the adipocytes we analyzed are from mammary glands before tumor formation, these results indicate that Nf1 plays a role in normal mammary adipocyte differentiation." (PMID 38799507, 2024). "We obtained cNFs from 4 individuals with NF1 (2 female and 2 male participants) and derived single cultures of NF1–/– SCs and NF1+/– FBs from each tumor." (PMID 38175707, 2024). "Loss of NF1, TSC1, or TβRII induced tumor cell-autonomous inflammatory reprogramming through alterations in chromatin accessibility and elevated IL6-JAK signaling." (PMID 38997291, 2024). "About 4–10% of NF1 patients carry large heterozygous genomic germline deletions that remove the NF1 tumour suppressor gene and its flanking regions." (PMID 38448973, 2024). "The NF-1 gene functions as a tumor suppressor, producing the protein neurofibromin, a GTPase-activating protein that regulates RAS activity." (PMID 39682300, 2024). "While instances of these tumor types have been documented in individuals with NF-1, the coexistence of both NETs on the duodenal ampulla and GISTs in the stomach is exceedingly uncommon." (PMID 39403336, 2024). "Increased drive/proliferation of NF1 SCdrives the formation of pNFs and cue the proliferation of fibroblasts and mast cells to form the tumor microenvironment." (PMID 39110684, 2024). "Evidence from NF1 mouse models suggested that the NF1-heterozygous microenvironment is responsible for promoting benign tumor formation while preventing malignant transformation." (PMID 39687068, 2024). "To test if there are Schwann cell-specific effects on phagocytosis, we removed BMDM from tumor-bearing mice incubated them with CFSE-labeled embryonic Nf1−/− Schwann cells." (PMID 38458648, 2024).